FOXP3 (forkhead box P3)
Diseases named in the same sentence as FOXP3 in open-access papers (continued):
Sharing a sentence is not in itself a finding about the gene and the disease.
cancer (continued). "Also, CD25 lost within activated T cells might be induced by competition for IL-2 between activated and regulatory T cells expressing higher levels of Foxp3, which has been directly associated with their potential to suppress the activation of effector T cells and correlated with cancer progression." (PMID 31616626, 2019). "Controlling PRMT5 activity is a promising strategy for cancer therapy in situations where host immunity against tumors is attenuated in a FOXP3 dependent manner." (PMID 30800128, 2019). "To assess the number of conventional and Tbet-expressing Foxp3+ Tregs in cancer patients, we analyzed 41 primary OPSCC tumors by three-color immunofluorescent confocal microscopy." (PMID 30658697, 2019). "The intriguing results reminded us the controversial role of FOXP3 in cancer immunity, especially in different cancer types." (PMID 30782783, 2019). "Next, the expression of hOX40 and mCTLA-4 was assessed on Tregs (CD4+ CD25+ Foxp3+) and conventional T cells (CD4+ CD25− Foxp3−) from tumors of mice with MC38 cancer." (PMID 30975201, 2019). "We found that the infiltration density of FoxP3+ Tregs was significantly higher in cancer tissue (P=0.024)." (PMID 31930120, 2019). "Nevertheless, the prognostic value of FoxP3+ T cell infiltration was found to depend foremost on the specific type of cancer." (PMID 30232514, 2019). "FoxP3+ regulatory T cells (Tregs) have a prognostic relevance in cancer, high Treg/CD4 T cell ratios correlate with more aggressive cancers." (PMID 31659168, 2019). "Accumulating evidence reveals that IL-17 + FOXP3+ T cells are shown highly in colon and esophageal cancers, inflammatory bowel disease, periodontitis, and rheumatoid arthritis." (PMID 31815635, 2019). "Cancer patients were divided into CD8 or FoxP3 low expression (scored as 0, n = 24, 8) groups, median expression (scored as 1, n = 22, 9) groups and high expression (scored as 2, n = 14, 43) groups." (PMID 31138162, 2019). "While Tregs are the major cell type expressing FOXP3 under physiological conditions, it has recently been found that FOXP3 was also expressed in a variety of cancers, such as ovarian, hepatocellular, pancreatic, and thyroid." (PMID 30782783, 2019). "The top 20 signal pathways enriched for FOXP3-bound genes mainly included cancer-related pathways, and these were almost abolished by the co-transfection of Gal-1." (PMID 29549328, 2018). "Tregs express FoxP3, which is important in the development and outcome of various diseases, including cancer, infectious diseases, and transplantation immunity." (PMID 30364052, 2018). "More recently, exogenous IL-21 was shown to inhibit the expression of FoxP3, the cardinal transcription factor associated with regulatory T cells, in human CD4+ T cells following encounter with cancer cells – in a manner similar to TGF-β blockade." (PMID 29854291, 2018). "These candidate molecules have the potential to be developed further for use as drug targets in autoimmune and inflammatory diseases or cancer, given the known relevance of FOXP3+ Tregs in these diseases." (PMID 29730990, 2018). "More importantly, we can suggest that this Notch/p65 cooperation can be active also in the regulation of Foxp3 signaling in cancer cells, as recently described in thyroid cancer and T-ALL." (PMID 30364244, 2018). "Due to its suppressive effect on the proliferation and metastasis of cancer cells, FOXP3 is considered a suppressor of breast cancer." (PMID 29549328, 2018). "Hundreds of FOXP3 target genes have been identified in both Treg cells and cancer cells so far, including HER2/ERBB2, SKP2, CD44, BRCA1, p21, and LATS2." (PMID 30011797, 2018). "More importantly, KEGG analysis revealed that the enriched signal pathways, related to the target genes of FOXP3, are mainly involved in cancer-related pathways, and these were almost abolished by co-transfection with Gal-1." (PMID 29549328, 2018).
cancer (continued). "Foxp3-expressing Treg cells limit anti-tumour responses and allow the persistence and growth of cancer." (PMID 29102676, 2018). "In addition, expression of FOXP3 in cancer cells might be associated with immunosuppression." (PMID 30103821, 2018). "Secondly, FOXP3 represses several key target genes in cancer development, such as BRCA1, CD44, HER2/ERBB2, and SKP2, providing a strong link between FOXP3 and DNA repair system, as well as FOXP3 and cell cycle regulation." (PMID 30011797, 2018). "Given the capability to suppress Foxp3 gene, it is possible to be tested as immunomodulators in cancer-related studies." (PMID 30400642, 2018). "The strong correlation of TGFβ activation with FOXP3 expression supports a crucial role of autocrine/paracrine TGFβ signaling in induction and maintenance of Tregs in diverse cancers." (PMID 29467463, 2018). "As FOXP3 has significant functions in immunological processes and cancer development, more studies are indeed required to further validate the role of post-translational modifications on FOXP3 functions in vivo." (PMID 30011797, 2018). "Commonly, Forkheadbox protein 3 (Foxp3), a transcription factor considered a marker of Tregs, is also expressed on cancer cells." (PMID 30060755, 2018). "An exception to this observation is that FOXP3 expression, a marker of Treg that has been shown to correlate to poor prognosis in various types of human cancer." (PMID 29276510, 2017). "In these experiments, we observed inhibition of T cell responses consistent with the level of FOXP3 expression induced in the suppressor population by cancer cell supernatants." (PMID 28239749, 2017). "The combined HR for FoxP3+ Tregs on cancer-specific survival was 0.70 (95% CI = 0.62–0.80, P < 0.001)." (PMID 29209232, 2017). "Studies have addressed and elucidated the role played by FOXP3 and Treg in countless autoimmune and infectious diseases as well as in more specific cases, such as cancer." (PMID 28603524, 2017). "In multivariate Cox regression analysis, high count of intratumoral CD68+ Mφ [HR: 2.70 (1.00–7.31); p=0.050] and high expression of FOXP3 in cancer cells [HR: 0.29 (0.09–0.91); p=0.034] were independent prognostic factors for overall survival." (PMID 28029650, 2017). "We noticed a positive reaction for Foxp3 not only in lymphocytes but also in some nuclei of cancer cells." (PMID 28831395, 2017). "Forced expression of FOXP3 significantly decreased the self-renewal ability of cancer stem cells, and thus the tumorigenic capacity." (PMID 28591725, 2017). "In this study, we have found that transcriptional factor FOXP3 is intrinsically down-regulated in stem cell-like cancer cells." (PMID 28591725, 2017). "FOXP3+ regulatory T regulatory (Treg) cells have an important role in immune homeostasis and cancer." (PMID 29136509, 2017). "Statitically, the overall expression of FOXP3 was much higher in cancer tissues than in normal adjacent tissues (p < 0.001)." (PMID 28716029, 2017). "In these assays, anti-TGFβ inhibited both the baseline FOXP3 induction observed in naïve T cells cultured alone, and that seen as a result of a 50% dose of cancer cell supernatants." (PMID 28239749, 2017). "In 106 NSCLC specimens, 41 cancer tissues were detected high FOXP3 expression and 65 cancer tissues showed low FOXP3 expression." (PMID 28716029, 2017). "We clarified the alterations of mRNA of major immune regulators PD-L1, FOXP3, CD80, CD40, and CD14 in PBMCs of cancer patients and the association of these alternations with disease progression." (PMID 26942414, 2017). "We then evaluated the co-expression of Helios and FoxP3 on Tregs from peripheral blood, NILs, and TILs of cancer patients." (PMID 28603527, 2017). "Future studies unraveling the detailed downstream effects of FOXP3-NFκB interaction on cancer stem cells would certainly broaden our understanding on how cancer stem cells are maintained and evolved." (PMID 28591725, 2017).
cancer (continued). "We observed a strong nuclear staining for Foxp3 in lymphocytes and cancer cells and strong membranous/cytoplasmatic reaction for CD4 and CD8, but low for CD25 and CTLA-4." (PMID 28831395, 2017). "We examined the effect of ectopic expression of FOXP3 on the several tumorigentic features of cancer cells using NSCLC cell lines (A549 and H460)." (PMID 28716029, 2017). "Forced expression of FOXP3 significantly decreased the self-renewal ability of cancer stem cells, as seen from the reduced number of colonospheres and the proportion of SP Cells, smaller successful rate of xenografts." (PMID 28591725, 2017). "Recent studies report Foxp3 is not only presented in Treg cells but also expressed in a variety of cancer cells." (PMID 28923073, 2017). "A similar positive correlation between FoxP3 and PD-1 was also observed in circulation in cancer patients (rs = 0.678, p = 0.02)." (PMID 28603527, 2017). "Data from patients suffering from a wide range of cancer types has further indicated that there appears to be a positive correlation between increased number of intra-tumoral FoxP3-expressing CD4+ T cells and poor prognosis for cancer patients." (PMID 28970798, 2017). "One further immune cell population of particular interest in cancer treatment are FoxP3-expressing regulatory T cells (Tregs)." (PMID 28970798, 2017). "For example, Foxp3 is over-expressed in breast, gastric, and thyroid cancer, and it also closely correlated with progression and prognosis of these cancers." (PMID 28923073, 2017). "In this study, we have investigated the ability of IL-21 to inhibit FOXP3 induction in purified naïve CD4 T cells in the context of culture supernatants from a number of cancer cell lines." (PMID 28239749, 2017). "It suggested that patients with high stromal infiltration of TILs, lower count of FOXP3+ Tregs and CD68+ Mφ in stromal site, and high expression of FOXP3 in cancer cells had longer survival of OS." (PMID 28029650, 2017). "And high count of intratumoral CD68+ Mφ and high expression of FOXP3 in cancer cells were independent prognostic factors for overall survival." (PMID 28029650, 2017). "In this study, we have found that FOXP3 is significantly down-regulated in cancer stem cell-like cancer cells." (PMID 28591725, 2017). "In some other types of cancers, FOXP3 has also been shown to promote cancer growth, migration and invasion." (PMID 28716029, 2017). "In multivariate Cox regression analysis, high count of intratumoral CD68+ Mφ and high expression of FOXP3 in cancer cells were independent prognostic factors for overall survival." (PMID 28029650, 2017). "Taken together, we have found that FOXP3 is significantly down-regulated in cancer stem cell-like cancer cells." (PMID 28591725, 2017). "The TGFβ1 and FoxP3 shared pathways induce an upregulated expression of VEGF which increases cancer vascularity and progression." (PMID 28053982, 2016). "An intratumoral increase in COX-2 and PGE2 levels is strongly correlated with the upregulation of FoxP3 and the suppressive capabilities of Tregs in several human cancers." (PMID 28053982, 2016). "Treg is characterized by expression of Foxp3 and plays an important role in the cancer immunosuppressive mechanism." (PMID 27602763, 2016). "Further defining Tregs by expression of GARP and LAP showed that FoxP3−LAP+ Tregs and activated FoxP3+/–Helios+GARP+LAP+Tregs were significantly expanded in cancer patients." (PMID 26885615, 2016). "We observed a lower representation of CD25+ and FoxP3+ TILs in advanced cancers and a reduction of blood Treg frequency after the excision of pT3–pT4 tumors." (PMID 26927070, 2016). "Several recent clinical trials have shown that depletion of CCR4-expressing FoxP3+CD4+ Treg cells by anti-human CCR4 monoclonal antibody is a promising approach to augment antitumor immune responses in cancer patients." (PMID 27177223, 2016).
cancer (continued). "GARP/LAP expression on FoxP3+Helios− Tregs were significantly lower than their expression on FoxP3+Helios+ and FoxP3−Helios+ in healthy donors and cancer patients." (PMID 26885615, 2016). "A recent consensus statement by The Association for Cancer Immunotherapy (CIMT) immunoguiding program (CIP) concluded that minimally required markers of human Treg are CD3, CD4, CD25, CD127, and Foxp3." (PMID 27330811, 2016). "Recently, a great interest in Foxp3+T cells led to studies of different type of cancers including NSCLC." (PMID 27602763, 2016). "Cyclophosphamide inhibits the generation and function of FOXP3+ Tregs in humans with various cancers." (PMID 27777963, 2016). "In previous studies, CD3, CD4, CD45RO, CD8, Foxp3+T cells and Myeloid-derived suppressor cells (MDSCs) are the most common infiltrating immune cells tested in cancers." (PMID 27602763, 2016). "It is upregulated in naive T cells, B cells, in CD4+CD25+Foxp3+ regulatory T cells, and in various human carcinomas, and suppresses immune responses by producing extracellular adenosine." (PMID 27471640, 2016). "In conclusion, we have, for the first time, identified direct and indirect target genes of cancer cell-derived Foxp3 in TSCC cells." (PMID 25779374, 2015). "These cells can be generated in the bone marrow in response to factors such as IL-6, GM-CSF, IL-1β, TNFα and have been shown to contribute to cancer immune evasion by suppressing T cell functions and promoting activation and expansion of Foxp3+ Tregs cells." (PMID 26109431, 2015). "Although most investigations have reported that FOXP3 is strictly expressed in Treg cells, FOXP3 can also be expressed in cancer cells and acts as a cancer repressor." (PMID 26441996, 2015). "Cancer cell-derived Foxp3 directly regulate the transcription of genes that affect certain internal biological processes of TSCC cells, and indirectly influence the extracellular microenvironment." (PMID 25779374, 2015). "Significant differences were found with reference to the percentage of CD4 + CD25 + FOXP3+ Treg lymphocytes in malignant and non-malignant tumors between individual groups of patients (Kruskal-Wallis test; p = 0.003)." (PMID 26077607, 2015). "Ronald J reviewed 58 studies including 16 different malignant tumors and found that the prognostic value of FoxP3 varies widely even in the same cancer type." (PMID 26604855, 2015). "Further improved understanding of FoxP3+ Treg subsets in different human cancers will likely enable the development of more precise and effective immunotherapies." (PMID 26462617, 2015). "Recently Foxp3+CD4+ T cells became an object of great interest in studies of different cancer types as well as in NSCLC." (PMID 26604855, 2015). "Previous research has reported TCR controlling Foxp3 expression and Treg generation via Akt15, 16, and isoliquiritigenin was reported as an inhibitor of Akt in cancer cells." (PMID 26370586, 2015). "Our data suggest that cancer cell-derived Foxp3 directly regulates the transcription of genes that affect certain internal biological processes of TSCC cells, and indirectly influences the extracellular inflammatory micro-environment." (PMID 25779374, 2015). "Studies have confirmed that inflammatory activate immune cells product cytokines, such as NF- κB, STAT3, AP-1, FOXP3 and interleukin, which can stimulate cancer cell proliferation and survival." (PMID 25956656, 2015). "Although Foxp3+CD4+ T cells can potentially promote cancer progression, they can also attenuate inflammation." (PMID 26604855, 2015). "Cancer cell-derived Foxp3 directly regulates the transcription of genes that affect certain internal biological processes of TSCC cells, and indirectly influences the extracellular microenvironment." (PMID 25779374, 2015). "In human cancers, FoxP3+ Tregs were shown to kill macrophages and monocytes and suppress their protumor effect." (PMID 26462617, 2015).
cancer (continued). "This suggests that cancer cell-derived Foxp3 indirectly affect the inflammatory microenvironment of TSCC." (PMID 25779374, 2015). "More recently, we have demonstrated that these regulatory cells (e.g. factor forkhead box P3 (Foxp3) positive Tregs and tolerogenic dendritic cells) in cancer patients are subject to regulatory cytotoxic T cells themselves." (PMID 26176858, 2015). "Based on a study showing that in a wide variety of cancers the infiltrating Foxp3+ cells were functional Tregs, making it likely that the Foxp3+ cells detected in our study reflect Tregs." (PMID 26357849, 2015). "The comparison between CRC patients and healthy donors (HD) revealed that LAP expression in CD4+Foxp3+ T cells isolated from PBMCs was significantly increased in cancer patients (CRC: 18.8%±9.2% vs. HD: 7.8%±3.3%)." (PMID 25268580, 2014). "Several carcinoma tissues and cultured cancer cell lines demonstrate the expression of Foxp3 and IL-10, suggesting that cancer cells induce the Treg cell-like immunoregulatory milieu to evade immunosurveillance." (PMID 25132998, 2014). "We found that the population of LAP-positive CD4+Foxp3+ Tregs significantly increased in peripheral blood and cancer tissues of CRC patients as compared to that in the peripheral blood and tissues of healthy subjects." (PMID 25268580, 2014). "The enrichment of CD4+Foxp3+LAP+ Tregs in the peripheral blood of CRC patients can be potentially used for monitoring cancer immunotherapy in clinical settings." (PMID 25268580, 2014). "Foxp3-positive T cells are conventionally thought to suppress antitumor immunity, resulting in poor clinical outcomes in cancer patients." (PMID 25461761, 2014). "The role of Foxp3-positive cells in the clinical outcome of cancer patients is remains controversial." (PMID 25461761, 2014). "ix) Finally, localization of CD68+ (H2) and CD163+ (I2) macrophages close to carcinoma cells as well as high expression of FoxP3 (O2), L1CAM (P3) and vimentin (R), respectively, tended to be associated with higher grading (S)." (PMID 24797069, 2014). "A similar trend, although not being significant, was observed for CD68+ macrophages located in close proximity to carcinoma cells (H3) as well as to FoxP3+(CD4+) T cells (F)." (PMID 24797069, 2014). "In contrast, FoxP3 expression was markedly increased in carcinoma cells being detectable at score 2 in 60% (% cells) and 80% (intensity), respectively." (PMID 24797069, 2014). "By discriminating Foxp3 expression of cancer cells from infiltrating Treg and correlating with overall survival over a long-term follow-up we provide new insights in its prognostic significance." (PMID 23382847, 2013). "The % of blood FOXP3+ Tregs in women whose cancers showed a poor pathological response (grades 1 and 2) to NAC (1.50 ± 0.15%) remained high (5 fold increase)." (PMID 23320561, 2013). "Foxp3 is a master regulator of a class of immunosuppressive T cell, that has a central role in cancer progression." (PMID 23349906, 2013). "They demonstrated in vitro, the generation of iTreg cells with similar phenotype (except for FOXP3) in co-cultures simulating some of the features unique to the human cancer in which equivalent Treg cells were observed." (PMID 23874336, 2013). "In summary, our data indicated that Tyr-342F phosphorylation of FOXP3 is involved in the inhibitory regulation of cancer malignancy by SKP2, VEGF-A, and MMP9 expression." (PMID 24155921, 2013). "We next examined Treg and cancer cells for a detailed expression analysis of Foxp3, IL-10, and TGF-β by immunohistochemistry." (PMID 23382847, 2013). "Our study, to the best of our knowledge, has shown for the first time that the level (%) of circulating FOXP3+ Tregs predicted the likely response to NAC – high levels resulting in poor pathological responses in the cancers in the breast." (PMID 23320561, 2013).